MTOR (mechanistic target of rapamycin kinase)
Diseases named in the same sentence as MTOR in open-access papers (continued):
Sharing a sentence is not in itself a finding about the gene and the disease.
cancer (continued). "mTOR plays a pivotal role in cell growth and metabolism and for this reason it is reasonable to suppose the existence of an association between the mTOR pathway activity and cancer." (PMID 29692710, 2018). "Because the UPR was not responsible for the phenotype of ER-stress-sensitivity of RAC1-depleted cells, we turned our attention to RAC1/cancer-linked kinase signalling pathways PI3K/AKT/MTOR and RAF/MEK/ERK." (PMID 29329780, 2018). "mTOR is an important growth regulator and is usually very active in cancer cells due to mutations in regulatory pathways or the mTOR itself." (PMID 29844464, 2018). "Somatic mutations in MTOR which deregulate and activate its kinase are known to occur in several cancer types, predominantly RCC in which mutation is seen in about 5%." (PMID 30256787, 2018). "Previous studies has demonstrated that PI3K/Akt/mTOR pathway is associated with drug-induced autophagy in cancer cells." (PMID 30153855, 2018). "Another signalling pathway associated with energy-associated cancer cell growth and survival is the mTOR pathway that senses cellular energy, oxygen levels, and nutrient to stabilise cell growth and survival." (PMID 30544833, 2018). "The DNA damage inducible transcript 4 (DDIT4) is induced by cellular stress conditions and regulates the mTOR activity, and also its abnormal expression has been linked to multiple diseases, including malignant tumors." (PMID 29707520, 2018). "We identified significant enrichments in cell-growth and cancer-associated pathways, such as the mTOR signaling pathway and the ErbB signaling pathway." (PMID 30093865, 2018). "Consistent with its pivotal role on controlling cell function, mTOR deregulation is often associated with the onset of diseases such as neurodegeneration, cancer and diabetes." (PMID 29772672, 2018). "Mammalian target of rapamycin (mTOR) is associated with cell proliferation, stress, and cancer progression." (PMID 30400561, 2018). "Previous studies show that mTOR inhibitors decrease the risk of cancer development after kidney transplantation." (PMID 30473931, 2018). "This review focuses on the downstream mTOR-regulated processes that are implicated in the “hallmarks” of cancer with focus on mTOR’s involvement in proliferative signalling, metabolic reprogramming, angiogenesis and metastasis." (PMID 29301334, 2018). "Alterations of sialylation of the PI3K pathway molecules cause inactivation of oncogenes like PI3K/mTOR resulting in regression of cancer." (PMID 29434218, 2018). "Proteins associated to the PI3K/AKT/mTOR signaling pathway are widely used targets for cancer treatment, and in recent years they have also been evaluated as putative targets in trypanosomatids parasites, such as Trypanosoma cruzi." (PMID 30544836, 2018). "In fact, compelling evidence has shown that aberrant activation of mTOR is associated with the development and progression of several types of cancers." (PMID 30110936, 2018). "Several genetic mutations have been reported that lead to PI3K/AKT/mTOR pathway activation in cancer." (PMID 30061533, 2018). "While mutation to TSC1/TSC2 and mTOR are rare occurrences in cancer, mutation to components higher in the signalling pathway are much more common." (PMID 29301334, 2018). "miR-100 has been consistently linked to mTOR in the literature, where it has been shown to regulate proliferation and migration via its effects on mTOR, particularly in cancer cells." (PMID 29343687, 2018). "Previous studies have shown reduced risk of cancer development after conversion of CNIs into mTOR inhibitors." (PMID 30473931, 2018). "In sporadic cancers, mTOR activation is the result of amplification/activation mutations in genes encoding upstream tumor signal transduction cascades or deletion/inactivation of tumor suppressors." (PMID 30105018, 2018).
cancer (continued). "We noted that JAK2/STAT3, TNF-α, mTOR/p70S6K or mTOR/p/0S6K/4E-BP1, and PI3K/Akt/mTOR signaling pathways associated with melittin in cancers were in accordance with the signaling pathway IDs of hsa04630, hsa04668, hsa04150, and hsa04151." (PMID 29854840, 2018). "Recent studies have demonstrated that inhibition of PI3K/AKT/mTOR pathway is associated with triggering autophagy and apoptotic cell death in cancer cells." (PMID 30096805, 2018). "Incidence and risk of de novo cancer development after kidney transplantation according to mTOR inhibitor treatment in time-dependent model." (PMID 30473931, 2018). "Based on our observations, we suggest that translation, under the control of mTOR signaling, is an important determinant of the susceptibility of cancer cells to ferroptosis." (PMID 29492203, 2018). "Mammalian/mechanistic target of rapamycin (mTOR) complexes are known downstream effectors of many cancer-causing mutations, which are thought to regulate cancer cell survival and growth." (PMID 30347859, 2018). "Given the central role of mTOR signaling in regulating fundamental biological events, there is a predictable association between mTOR pathway activation and cancer." (PMID 29351204, 2018). "They revealed that the cancer cells adjusted their glucose metabolic status by mTOR pathway regulating the expression of molecule associated with glucose and lactate uptake and acquired the resistance to hypoxia condition induced by anti-angiogenic therapy." (PMID 28068944, 2017). "The phosphoinositide-3-kinase (PI3K)/Akt/mammalian target of rapamycin (mTOR) pathway is commonly activated in cancer by several mechanism including activating mutations of PIK3CA or AKT1 and or loss of phosphatase and tensin homolog (PTEN)." (PMID 29156674, 2017). "The PI3K/Akt/mTOR pathway regulates cell growth and proliferation and is often dysregulated in cancer due to mutation, amplification, deletion, methylation and post-translational modifications." (PMID 28225015, 2017). "A growing body of evidence indicates that 4E-BP1 is a critical effector of mTOR signaling through translational control of key oncogenic mRNAs that encode proteins for cell-cycle progression, cell survival, angiogenesis, cancer progression, and metastasis." (PMID 29263324, 2017). "Signaling via the mTOR pathway has been implicated in a broad range of chemoresistant cancers, and rapamycin has been shown to reverse multidrug resistance." (PMID 28539118, 2017). "One inhibitor of MEK, PD98059, also suppressed the same cancer-associated phenotypes of SYK-positive cells by decreasing phosphorylated ERK1/2 but increasing phosphorylated mTOR." (PMID 29137391, 2017). "A recent study on cell lines has demonstrated that the presence of PIK3CA mutations can sensitize cancer cells to mTOR inhibitor, everolimus." (PMID 28392480, 2017). "Somatic mutations in the PIK3CA gene, which encodes PI3K, are cell–intrinsic alterations in many cancers and often confer constitutive activation of the downstream mTOR signaling pathway." (PMID 28959684, 2017). "Previous pre-GWAS studies demonstrated that genetic variants in PI3K/AKT/mTOR pathway were associated with cancer risk, including PCa." (PMID 28977864, 2017). "mTOR is deregulated in many disease conditions, and upregulation of mTOR is implicated in the development of cancer and the maintenance of cancer SC (CSC)." (PMID 28831205, 2017). "We also found that in cells expressing cancer-associated hyperactivating MTOR mutations, the growth inhibitory effects of BC-LI-0186, rapamycin, and INK128 were comparable to the inhibitory effects on S6K phosphorylation." (PMID 28963468, 2017).
cancer (continued). "One target of PI3K signaling that has commonly been implicated in cancer is mammalian target of rapamycin (mTOR)." (PMID 27926496, 2017). "mTOR signaling is activated in the majority of cancers owing to mutations in upstream signaling components including RAS, PI3K, PTEN, TSC1, TSC2, and LKB11." (PMID 29263324, 2017). "AKT/mTOR is one of the most critical pathways in cancer stem cell growth, and is implicated in transition of cancer stem cells to endothelial cells." (PMID 29156702, 2017). "We found significant involvement of mutated promoters for MAPK signaling, ERBB signaling, MTOR signaling, and transcriptional mis-regulation in cancer pathways." (PMID 28333948, 2017). "In PKD, it is well described that alterations of several components of the PI3K/AKT/mTOR pathway, already found in cancer, are implicated in the hyper-proliferation of renal tubular cells, such as TSC." (PMID 28353628, 2017). "Deregulated mTOR signaling has been implicated in major diseases, including cancer, metabolic disorders, neurological diseases, and inflammation." (PMID 28400571, 2017). "Deregulation of mTOR signaling is associated with aging and development of human diseases, including cancer, obesity, type 2 diabetes and neurodegeneration." (PMID 28086984, 2017). "The PI3K/AKT/mTOR pathway is altered in many human cancers by activating mutations, aberrant receptor tyrosine kinase signaling or inactivating mutations in tumor suppressor genes like PTEN (phosphatase and tensin homolog)." (PMID 28724379, 2017). "In these studies, abnormally elevated levels of mTOR have been linked with several human cancers including prostate, pancreas, liver, breast, colorectal, urinary tract, and female reproductive organs." (PMID 28659828, 2017). "mTOR as well as some of the targets of the mTOR kinase signaling are overexpressed or mutated in cancer, and it is regarded as a promising target for anticancer treatment." (PMID 29167516, 2017). "The results of Gene Set Enrichment Analysis (GSEA) indicated that cells on chitosan substrates increased the genes related to mTOR, eIF4, Cdc42, and Ras signaling pathways, which are associated to the cancer progression and invasiveness." (PMID 28367998, 2017). "Recent studies have indicated that modulation of the AMPK/mTOR pathway is associated with the triggering of autophagy in cancer cells." (PMID 29029506, 2017). "DDIT4 gene encodes a protein whose main action is to inhibit mTOR under stress conditions whilst several in vitro studies indicate that its expression favors cancer progression." (PMID 28484222, 2017). "For example, Oscillibacter, Alistipes, and Clostridiales are associated with cancer, metabolic diseases, aging, and cardiovascular disease, mainly by influencing the mechanistic target of the rapamycin (mTOR) signaling pathway." (PMID 29123168, 2017). "In summary, the rDNA copy number and sequence can change in cancer, with high mTOR activity associated with contractions and DNA damage sensitivity." (PMID 28640831, 2017). "Recent studies researched the associations of core genes in the pTEN/AKT/mTOR pathway polymorphisms with the cancer susceptibility; however, the results are inconclusive." (PMID 29259266, 2017). "Among these signaling pathways implicated in cancers, it is worth noting that PI3K/Akt/mTOR is the most frequently altered pathway in human cancers and controls many important processes." (PMID 28335497, 2017). "We evaluated retrospectively with a next generation sequencing (NGS) approach using a pre-designed cancer panel the mutation burden of 32 lesions from 22 metastatic RCC patients treated with at least one tyrosine kinase or mTOR inhibitor." (PMID 27741505, 2017). "PRL-3 has specifically been implicated in activation of acknowledged cancer progression pathways like phosphatidylinositol-3 kinase, regulating mTOR activation, Src tyrosine protein kinase, epidermal growth factor receptor (EGFR), and ERK." (PMID 29190795, 2017).
cancer (continued). "Early studies on cell death regulation dependent on the caspase-9 protein have revealed the participation of Akt and small G protein p21-Ras kinases, and the PI3K–Akt–mTOR signaling pathway dysregulation has been extensively associated with cancer." (PMID 28632179, 2017). "Use of mTOR inhibitors in combination with trastuzumab or lapatinib is currently underway for cancers that are refractory to the anti-ERBB2 therapy, mostly caused by aberrant PI3K/Akt/mTOR signaling." (PMID 29050229, 2017). "Proteins that regulate the mammalian target of rapamycin (mTOR), as well as certain targets of the mTOR kinase, are overexpressed or mutated in cancer." (PMID 29179457, 2017). "The mTOR signaling pathway is frequently overactivated in cancer cells, either by mutations of upstream components of the pathway or by mutations of mTOR itself." (PMID 29104248, 2017). "Persistently activated PI3K/Akt/mTOR axis signaling is associated with the development of cancer (Cancer Genome Atlas Research Network, 2008)." (PMID 28491867, 2017). "Somatic mutations of potential driver genes such as ARID1A, ATM, and MTOR promoted cancer growth, and many mutations were generated due to MMR deficiency." (PMID 28974240, 2017). "The selected compound BC-LI-0186 efficiently inhibited leucine-dependent mTORC1 activity and the growth of cancer cells that express drug-resistant MTOR mutations." (PMID 28963468, 2017). "Given mutational evidence for mTOR activation in the human cancer genomes with loss of ribosomal DNA copies, we analyzed ribosomal DNA in hematopoietic stem cells derived from mice under conditions of mTOR activation." (PMID 28640831, 2017). "Collectively, these events caused by the activated PI3K/AKT/mTOR pathway suppress apoptosis of cancer cells." (PMID 28490807, 2017). "mTORC1 hyperactivation is furthermore frequently observed in sporadic cancers, either through activating mutations of upstream effectors of mTORC1 or through activating mutations of mTOR itself." (PMID 28280521, 2017). "Activation of mTOR signaling has been shown to be a hallmark of cancer and has been linked to cell growth and cell cycle progression." (PMID 29254159, 2017). "Together, these results suggest that targeting the leucine-sensing activity of LRS provides a strategy to overcome drug resistance caused by MTOR mutations in cancer." (PMID 28963468, 2017). "Previous studies reported that increasing both E2F and mTOR activity causes synergistic cell death in cancer cells." (PMID 28076433, 2017). "Genes that encode components of the PI3K–Akt–mTOR pathway are frequently mutated in cancer, but despite few mutations have been characterized in mTOR, many tumor types present mTOR hyperactivation, thus promoting tumorigenesis." (PMID 28932704, 2017). "To monitor the effect of BC-LI-0186 on cancer-associated MTOR mutations, we first determined the extent of their leucine dependency for S6K phosphorylation." (PMID 28963468, 2017). "Our data demonstrated that several genes in key cancer pathways (EGFR-PI3K-Akt-mTOR, NOTCH, NF-κB, DNA repair) were mutated, suggesting their potential use as predictive markers for targeted therapies to improve survival and outcome of NPC patients." (PMID 28256603, 2017). "In conclusion, this meta-analysis was performed included the latest publications, and provided a more precise prevalence estimate for associations of five SNPs of pTEN/AK/mTOR pathway with the risk of cancer." (PMID 29259266, 2017). "Dysregulation of the PI3K–Akt–mTOR signal transduction pathway has been shown to be associated with some carcinomas and has been implicated in the apoptotic intrinsic pathway too; this pathway performs essential functions in cellular growth regulation." (PMID 28632179, 2017).
cancer (continued). "This would indicate a potential therapeutic strategy to target oncogenic mTOR signalling in cancers harbouring IDH1/2 mutations." (PMID 27624942, 2016). "CRISPR/Cas9-mediated EIF4EBP3 gene disruption in human cancer cells mitigated the inhibition of translation and proliferation caused by prolonged treatment with mTOR inhibitors." (PMID 27319316, 2016). "Given that rs2295080, rs1883965, rs1034528 and rs17036508 showed a potential association with cancer susceptibility, we further explored their relationship with mTOR transcript expression levels using the SNPexp web tool." (PMID 27462867, 2016). "These TSC1/TSC2 loss of function mutations activate mammalian target of rapamycin (mTOR) protein kinases, which promote both cell proliferation and survival, have been implicated in various types of cancer." (PMID 27377753, 2016). "A large-scale multicenter study with detailed individual data is needed to further validate gene-gene and gene-environment interactions between mTOR genetic polymorphisms and cancer risk." (PMID 27533457, 2016). "Aberrant mTOR signaling pathway activation through oncogene stimulation or loss of tumor suppressors contributes significantly to cancer initiation, development and chemotherapy resistance." (PMID 26940018, 2016). "Other signaling components of the upstream and downstream mTOR pathways are also frequently altered during proliferation dysregulation, which is associated with poor cancer prognosis." (PMID 27835987, 2016). "In PG, the top three most enriched pathways were the ErbB, TGF-β, and mTOR signaling pathways often associated with various cancers." (PMID 27379121, 2016). "There are some data on the activation of PTEN/PI3K/AKT/mTOR pathway in cancers arising in BRCA mutation carriers." (PMID 27555886, 2016). "Accumulating evidence suggests that mTOR is the driving force for aging and aging is the selecting force for cellular mutations leading to cancer." (PMID 26934328, 2016). "The three MLL2 oncomodules have previously been linked to cancer, with MTOR and E2F1 specifically involved in tumorigenesis in HNSC." (PMID 27095575, 2016). "Our data raise the intriguing possibility that cancer therapeutic regimens designed to inhibit mutated IDH1/2 would be expected to reduce oncogenic mTOR activity." (PMID 27624942, 2016). "The PI3K/Akt/mTOR pathway is often dysregulated in cancer due to mutations, deletions, amplifications, methylation changes and post-translational modifications." (PMID 27507059, 2016). "Overactivation of mammalian target of rapamycin (mTOR) is observed in many human OS tissues, which is often associated with cancer progression and poor prognosis." (PMID 27385099, 2016). "Integrated risk estimates of clinical evidence reveal that the mTOR SNPs studied to date only have a mild effect on cancer development." (PMID 27462867, 2016). "Mechanistic target of rapamycin (mTOR) is a central regulator of energy storage and consumption, and is implicated in deleterious states such as cancer, metabolic diseases and ageing." (PMID 27471110, 2016). "In fact, the dysregulation of mTOR-dependent cellular homeostasis maintenance is associated with several human diseases such as cancer and considerable research efforts have been made to efficiently inhibit mTOR signaling." (PMID 28040803, 2016). "We estimated the summary odds ratios (ORs) and corresponding 95% confidence intervals (CIs) for mTOR polymorphisms and cancer risk, and used the model-free approach to investigate the biological effect of each polymorphism." (PMID 27462867, 2016). "PI3K/AKT/mTOR signalling pathway proteins play significant role in cell proliferation and metabolism and in cancer associated pathophysiological conditions." (PMID 27380262, 2016).